DDX6 (DEAD-box helicase 6)
Description:
Essential for the formation of P-bodies, cytosolic membrane-less ribonucleoprotein granules involved in RNA metabolism through the coordinated storage of mRNAs encoding regulatory functions. Plays a role in P-bodies to coordinate the storage of translationally inactive mRNAs in the cytoplasm and prevent their degradation. In the process of mRNA degradation, plays a role in mRNA decapping. Blocks autophagy in nutrient-rich conditions by repressing the expression of ATG-related genes through degradation of their transcripts.
Synonyms: HLR2; RCK; Rck/p54; IDDILF; P54
Tractability: Small molecule: a structure with a bound ligand is known. Antibody: its Gene Ontology location is reachable by antibodies, with high confidence. PROTAC: UniProt records ubiquitination sites on it; ubiquitination databases record sites on it; its protein half-life has been measured; a small molecule that binds it is known.
Target class: Enzyme; Hydrolase
Gene: Protein-coding gene on chromosome 11 (118,747,763 to 118,791,226, reverse strand). Ensembl gene ENSG00000110367.
Subcellular location: Cytoplasm, P-body; Cytoplasm; Nucleus; Cytoplasm, Cytoplasmic ribonucleoprotein granule
Subcellular location (Human Protein Atlas): Cytoplasmic bodies; Cytosol; Midbody; Plasma membrane
Pathways (Reactome):
Metabolism of RNA: mRNA decay by 5' to 3' exoribonuclease
Gene Ontology:
Molecular function: cadherin binding; protein binding; protein domain specific binding; RNA binding; helicase activity; RNA helicase activity; ATP binding; ATP hydrolysis activity; nucleic acid binding
Biological process: miRNA-mediated gene silencing by inhibition of translation; negative regulation of translation; P-body assembly; viral RNA genome packaging; deadenylation-dependent decapping of nuclear-transcribed mRNA; nuclear-transcribed mRNA catabolic process, deadenylation-dependent decay; pre-mRNA catabolic process; stress granule assembly; spermatid differentiation; spermatogenesis
Cellular component: cytoplasm; cytoplasmic ribonucleoprotein granule; cytoplasmic stress granule; cytosol; membrane; nucleus; P-body; RISC complex; RNA decapping complex; adherens junction; chromatoid body; concave side of sperm head; heterochromatin; outer dense fiber; perinuclear region of cytoplasm; sperm annulus
Genetic constraint (gnomAD): Loss-of-function variants: 1 observed, 37.1 expected, observed/expected ratio (o/e) 0.027, 90% interval 0.009 to 0.13. The upper end of that interval is the gene's LOEUF score, 0.13, which puts it in group 1 of 6, group 1 being the genes least tolerant of losing a copy. Missense variants: 203 observed, 452.09 expected, observed/expected ratio (o/e) 0.45, 90% interval 0.4 to 0.5. Synonymous variants: 150 observed, 157.49 expected, observed/expected ratio (o/e) 0.95, 90% interval 0.83 to 1.09.
Cancer hallmarks: angiogenesis (promotes); escaping programmed cell death (promotes); proliferative signalling (promotes)
Homologues: Orthologues: chimpanzee DDX6 (100% identical), macaque DDX6 (100% identical), dog DDX6 (99% identical), pig DDX6 (99% identical), rabbit DDX6 (99% identical), rat Ddx6 (98% identical), mouse Ddx6 (98% identical), tropical clawed frog ddx6 (95% identical), guinea pig DDX6 (93% identical), zebrafish ddx6 (89% identical). Paralogues in human: DDX46 (30% identical), EIF4A1 (29% identical), EIF4A2 (29% identical), DDX43 (28% identical), DDX19B (27% identical), DDX4 (27% identical), DDX19A (27% identical), DDX53 (27% identical), EIF4A3 (27% identical), DDX23 (27% identical), DDX20 (26% identical), DDX39A (26% identical), and 26 more.
Diseases named in the same sentence as DDX6 in open-access papers:
DDX6 is named in the same sentence as 57 diseases in open-access papers, as found by Europe PMC text mining. Sharing a sentence is not in itself a finding about the gene and the disease. The quoted sentences say what the papers report.
gastric cancer (9 papers, 2017 to 2025). A primary or metastatic malignant neoplasm involving the stomach. "DDX6 as oncogene in gastric cancer cells through promotion of c-Myc expression by association with the mRNA of c-Myc22." (PMID 39013964, 2024). "In gastric cancer cells, DDX6 has been found to interact with c-Myc mRNA and thus enhance the mRNA and protein expression of c-Myc." (PMID 38834947, 2024). "Previous studies have revealed the oncogenic role of DDX6 in gastric cancer, colorectal cancer, and glioblastoma." (PMID 38834947, 2024). "Since DDX6 plays an oncogenic role in multiple cancers including gastric cancer, colon cancer, and myeloid leukemia, we focused on the interaction between Rab3B and DDX6." (PMID 38834947, 2024). "In several cancer types including gastric cancer, colorectal cancer, and glioblastoma, DDX6 is found to play an oncogenic role." (PMID 38834947, 2024). "DDX6 is mainly localized in processing bodies (P-bodies) in gastric cancer cells, and a reduction in the DDX6 abundance in P-bodies leads to an increase in miR-143/145 expression by stabilizing the host pri-miRNA transcript NCR143/145." (PMID 38689093, 2024). "DDX6 is implemented in the regulation of MYC expression in gastric cancer." (PMID 37019990, 2023). "Taniguchi observed that DDX6 promotes the transcription of c-Myc in gastric cancer cells." (PMID 34233596, 2021). "In gastric cancer, miR-143 indirectly downregulates the expression of the human epidermal growth factor receptor (HER2), which is an upstream molecule of KRAS, by silencing DEAD/H-box RNA helicase 6 (DDX6)." (PMID 36233210, 2022). "In the current study, we aimed at revealing the function of DDX6 in HER2 and FGFR2 related human gastric cancer (GC) by using clinical samples and GC cell lines." (PMID 29987267, 2018). "DDX6 overexpression was observed in 60% of gastric cancer samples and 83% of FGFR2-positive cases, and DDX6 knockdown reduced FGFR2 and HER2 protein expression without affecting mRNA levels." (PMID 41303727, 2025).
viral infection (8 papers, 2011 to 2023). "Considering the presence of DDX6 in diverse contexts, such as cancer, virus infection, and stem cells, this new knowledge forms a foundation for DDX6 being a good therapeutic target." (PMID 36197846, 2022). "Given the important roles of DDX6 in viral infection, we investigated the role of DDX6 in EV71 infection." (PMID 34485180, 2021). "RIG-I knockdown reduced the production of IFN-β mRNA in response to NS1 mutant virus infection by up to 90%, whereas knockdown of DDX6 decreased IFN-β mRNA production by about 50–60%." (PMID 29949917, 2018). "We quantified the amount of DDX6 that re-localized to the assembly site after viral infection or transfection, and found that about 15–25% of total endogenous DDX6 proteins were located in the MTOC area after infection." (PMID 22022269, 2011). "In addition to the functional consequences of DDX6 in cancer and viral infection, DDX6 also plays multiple roles in facilitating translational repression in cell differentiation and embryogenesis." (PMID 36834609, 2023). "It is supported that DDX6 has pro- and antiviral roles in viral infections." (PMID 34485180, 2021). "In summary, the results in this study have revealed a unique and dynamic interaction between P body/stress granule proteins and foamy virus infection where Dcp1 negatively regulates viral RNA packaging but DDX6 is required for efficient encapsidation of virus genomes." (PMID 22022269, 2011). "Similarly, depletion of DDX6 or LSm14a, as might occur during the course of a viral infection, also results in P-body disassembly." (PMID 36877681, 2023). "The N protein of SARS-CoV-2 has been found to interact with several RNA helicases, including DDX1, DDX3, DDX5, DDX6, DDX21, and DDX10; among them, DDX1, DDX5, and DDX6 are essential for virus replication, while DDX21 and DDX10 restrict the viral infection." (PMID 38328580, 2023). "In the absence of foamy virus infection, DDX6 typically co-localized with Dcp1 in cytoplasmic P body granules." (PMID 22022269, 2011). "We have ruled out a possible role of DDX6 in transporting viral RNA and Gag to the MTOC area, and it is unclear how DDX6 is re-localized to the assembly site which occurs specifically only after virus infection or transfection." (PMID 22022269, 2011).
breast carcinoma (4 papers, 2022 to 2025). "Among these five proteins, the corresponding genes for three proteins, including COPG1, DCTN3, and DDX6, were located at least 1Mb away from the GWAS-identified breast cancer risk variants." (PMID 39468330, 2024). "Among these five proteins, the corresponding genes for proteins COPG1, DCTN3, and DDX6 were located at least 1 Megabase away from the GWAS-identified breast cancer risk variants." (PMID 39468330, 2024). "Both DCTN3 and DDX6 were associated with a decreased risk of breast cancer with p values of 1.01 × 10–3 and 3.25 × 10–4, respectively." (PMID 39468330, 2024). "In this first breast-tissue-based PWAS of breast cancer risk, we found that five proteins (COPG1, DCTN3, LSP1, DDX6, and DNAJA3) were significantly associated with overall breast cancer risk." (PMID 39468330, 2024). "Increased protein expression levels were associated with a decreased risk of breast cancer for DCTN3 and DDX6, with p values of 1.01 × 10–3 and 3.25 × 10–4, respectively." (PMID 39468330, 2024). "TGF-β induces P-body formation and EMT in mammary epithelial cells, while inhibition of P-body formation by knockdown of DDX6 reverses EMT and suppresses breast cancer metastasis, implying a prometastatic function of P-bodies during the progression of breast cancer." (PMID 39046443, 2024). "DDX6 and DNAJA3 both exhibited a negative association with breast cancer risk in this study." (PMID 39468330, 2024).
Intellectual disability (4 papers, 2022 to 2024). "Neurological disorders are also associated with P-body dysregulation as mutations in the DDX6 helicase prevent proper assembly of P-bodies and ultimately result in intellectual disability in humans." (PMID 35832192, 2022). "Interestingly, full-length mutant DDX6 protein is associated with another neurodevelopmental disorder in which a mutation in the DDX6 gene leads to several phenotypes including intellectual disability, as observed in PURA Syndrome." (PMID 36651277, 2023). "Moreover, rare mutations in DDX6 cause intellectual disability." (PMID 38536035, 2024).
B-cell lymphoma (3 papers, 2018 to 2024). "Among these genes, we found five genes, ATP5L, BCL9L, CD3G, CXCR5, and DDX6, that have been reported to be associated with the occurrence of B-cell lymphomas, a blood cancer caused by the disorder of immune functional B cells (also known as B lymphocytes) that attack invading pathogens." (PMID 36173765, 2022).
colorectal tumor (3 papers, 2009 to 2022). "In 1998, DDX6 (also known as rck/p54) was found high expression in human colorectal tumor tissues, but low expression in normal colorectal mucosa tissues." (PMID 35237592, 2022). "Previously, we reported that DDX6 is overexpressed in most malignant cell lines and clinical colorectal tumor samples and that DDX6 positively contributes to the pathogenesis of various cancers." (PMID 29987267, 2018). "Previously, we reported that the DDX6 is overexpressed in most malignant cell lines and clinical colorectal tumor samples examined, and that DDX6 positively contributes to c-Myc expression at the translation initiation step in various cancers." (PMID 29987267, 2018). "There are several examples of dyregulation of RNA helicases in cancer, mostly in the forms of overexpression including those of DDX5 and DDX6 which were reported to be overexpressed in colorectal tumor." (PMID 19161603, 2009).
glioblastoma (3 papers, 2021 to 2025). The most malignant astrocytic tumor (WHO grade IV). "DDX6 is involved in radio- and chemoresistance in glioblastoma, and TNFRSF6B suppresses CD95 ligand-induced apoptosis and chemotaxis in malignant glioma." (PMID 33936159, 2021).
glioma (3 papers, 2015 to 2021). A benign or malignant brain and spinal cord tumor that arises from glial cells (astrocytes, oligodendrocytes, ependymal cells). "Thus DDX6 may play a role in multiple cancers, and our results implicate DDX6 in the potential mechanisms contributing to glioma risk." (PMID 26610392, 2015). "A previous report identified rs73001406 as a candidate functional variant for glioma on 11q23.3, with PHLDB1 and DDX6 as potential target genes." (PMID 33169458, 2021). "A case-control study recruited 855 high-grade glioma patients from four different geographic regions of the US and belonging to five inherited glioma risk variants: 5p15.3 (TERT), 8q24.21 (CCDC26/MLZE), 9p21.3 (CDKN2B), 11q23.3 (PHLDB1/DDX6) and 20q13.3 (RTEL1)." (PMID 30909395, 2019).
colon cancer (2 papers, 2021 to 2024). "Additionally, DDX6 exhibited higher expression and modulated by miR-124 in colon cancer." (PMID 34158095, 2021).
Dystrophia myotonica (2 papers, 2017 to 2024). "As reported, many mRNAs exhibit an increased mis-splicing under pathological conditions, while the RNA helicase DDX6 can relieve this mis-splicing event, for example, overexpression of DDX6 can reduce the mis-splicing of Ppp2r5c and IR2 in the patients of myotonic dystrophy type 1 (MD1)." (PMID 38810698, 2024).
osteoarthritis (2 papers, 2021 to 2023). A noninflammatory degenerative joint disease occurring chiefly in older persons, characterized by degeneration of the articular cartilage, hypertrophy of bone at the margins and changes in the synovial membrane. "It was concluded that lncRNA CASC19 accelerated chondrocytes apoptosis and proinflammatory cytokine production to exacerbate osteoarthritis development through regulating the miR-152-3p/DDX6 axis." (PMID 34158095, 2021). "Moreover, CASC19 could accelerate chondrocyte apoptosis and proinflammatory cytokine production and exacerbate osteoarthritis development by regulating the miR-152-3p/DDX6 axis." (PMID 36769373, 2023).
prostate carcinoma (2 papers, 2023 to 2025). A carcinoma that arises from epithelial cells of the prostate gland. "In response to increased mRNA decay mediated by XRN1 and DDX6, DHX9 emerges as a significant target molecule in acquired resistance to bortezomib in PC3 prostate cancer cells." (PMID 39799471, 2025). "With siRNA screens, several of these were indicated in survival (DDX6, EIF4A3, PABPN1), growth (e.g., EIF5A, HNRNPH2, LRRC47, and NVL), and migration (e.g., NOL3 and SLTM) of prostate cancer cells." (PMID 37591798, 2023). "DDX6, NOL3, and RRP9 showed differential expression in RNA and protein data between primary cancer and CRPC, suggesting that these RBPs are regulated post‐transcriptionally in prostate cancer." (PMID 37591798, 2023).
vitiligo (2 papers, 2016 to 2022). Generalized well circumscribed patches of leukoderma that are generally distributed over symmetric body locations and is due to autoimmune destruction of melanocytes. "The results of a vitiligo GWAS in the Han Chinese population identified rs10876864-PMEL, rs638893-CXCR5/DDX6, and rs11417210-SLC29A3/CDH23 to be associated with vitiligo risk." (PMID 36008553, 2022). "Association analyses identified that rs638893 at 11q23.3 is associated with vitiligo in the Chinese Han population, and rs638893 is located in an intergenic region between CXCR5 and DDX6." (PMID 26870082, 2016). "Rs638893 located in an intergenic region between DDX6 and CXCR5 is associated with vitiligo." (PMID 26870082, 2016).
alcoholism (1 paper, 2020). "DDX6 has also been implicated in other neuropsychiatric disorders (alcoholism, other addictions, depression, schizophrenia), as well as is an increased in expression blood biomarker for suicide in our previous studies." (PMID 30862937, 2020).
Alzheimer disease (1 paper, 2025). A progressive, neurodegenerative disease characterized by loss of function and death of nerve cells in several areas of the brain leading to loss of cognitive function such as memory and language. "We identified four proteins (DSP, JUP, HRNR, and DDX6) that bind to amyloid‐beta (Aβ) oligomers derived from the brains of Alzheimer's disease (AD) patients." (PMID 40276647, 2025).
amyotrophic lateral sclerosis (1 paper, 2021). Amyotrophic lateral sclerosis (ALS) is a neurodegenerative disease characterized by progressive muscular paralysis reflecting degeneration of motor neurons in the primary motor cortex, corticospinal tracts, brainstem and spinal cord. "Analysis of RBM20 RNA binding by eCLIP reveals a gain-of-function preference of mutant RBM20 for 3′ UTR sequences that are shared with amyotrophic lateral sclerosis (ALS) and processing-body associated RNA binding proteins (FUS, DDX6)." (PMID 34732726, 2021).
Autoimmunity (1 paper, 2025). The occurrence of an immune reaction against the organism's own cells or tissues. "Beyond autoimmunity, our analysis identified genes with dual roles in AIDs and cancer, such as CDC37, DDX6, and MAPT, suggesting possible immune–oncogenic links." (PMID 40429780, 2025).
brain tumors (1 paper, 2015). "While most of the genes in the locus display somatic alterations in any cancer, only a small subset are mutated in brain tumors, notably PHLDB1 and DDX6." (PMID 26610392, 2015).
cervical cancer (1 paper, 2017). A primary or metastatic malignant neoplasm involving the cervix. "To examine the nuclear presence of DDX6 in human cell nuclei, we performed subcellular fractionation followed by WB on the HeLa human cervical cancer cell line, the transformed human embryonic kidney cell line HEK293T, and human embryonic stem cell-derived cardiomyocytes (hESC-derived CM)." (PMID 28216671, 2017).
developmental disability (1 paper, 2023). Disorders in which there is a delay in development based on that expected for a given age level or stage of development. "Patients with this DDX6 mutation exhibited a developmental disability with hypoplastic posterior corpus callosum and speech delay, which suggests that DDX6 may have a prominent role in neuronal development and cell differentiation." (PMID 36834609, 2023).
Flavivirus Infections (1 paper, 2020). Infections with viruses of the genus FLAVIVIRUS, family FLAVIVIRIDAE. "Decapping and 5′ to 3′ exonucleocytic degradation limits bunyavirus and flavivirus infections, with the decapping activator helicase DDX6 identified as an antiviral factor in both cases." (PMID 33109765, 2020).
HIV-1 infection (1 paper, 2021). The type species of lentivirus and the etiologic agent of acquired immunodeficiency syndrome (AIDS). "Thus, this novel antiretroviral compound colocalizes with HIV-1 Gag and with the host proteins ABCE1 and DDX6, all of which are components of HIV-1 assembly intermediates, and colocalizes with ABCE1 and DDX6 even in the absence of HIV-1 infection." (PMID 33148797, 2021). "Interestingly, our studies found that PAV-206 colocalizes with both of these host enzymes, ABCE1 and DDX6, in the absence of HIV-1 infection, suggesting that the compound acts on the host RNA-granule-related RNP complex that is the precursor of assembly intermediates, even in the absence of Gag." (PMID 33148797, 2021).
liver carcinomas (1 paper, 2013). An epithelial or non-epithelial malignant neoplasm that arises from the liver. "DDX6 protein levels are also frequently elevated in HCV-associated carcinomas, while being down-regulated in other liver carcinomas, suggesting a possible role in HCV-induced liver pathology." (PMID 23826300, 2013). "Thus the function of DDX6 in HCV replication needs further study in order to better understand the relationship and its possible link to hepatocellular carcinoma." (PMID 23826300, 2013).